IFI35 (interferon induced protein 35)
Description:
Acts as a signaling pathway regulator involved in innate immune system response. In response to interferon IFN-alpha, associates in a complex with signaling pathway regulator NMI to regulate immune response; the complex formation prevents proteasome-mediated degradation of IFI35 and correlates with IFI35 dephosphorylation. In complex with NMI, inhibits virus-triggered type I interferon/IFN-beta production. In complex with NMI, negatively regulates nuclear factor NF-kappa-B signaling by inhibiting the nuclear translocation, activation and transcription of the NF-kappa-B subunit p65/RELA, resulting in the inhibition of endothelial cell proliferation, migration and re-endothelialization of injured arteries. Beside its role as an intracellular signaling pathway regulator, also functions extracellularly as damage-associated molecular patterns (DAMPs) to promote inflammation when actively released by macrophage to the extracellular space during cell injury and pathogen invasion. Macrophage-secreted IFI35 activates NF-kappa-B signaling in adjacent macrophages through Toll-like receptor 4/TLR4 activation, thereby inducing NF-kappa-B translocation from the cytoplasm into the nucleus which promotes the release of pro-inflammatory cytokines.
Synonyms: IFP35
Tractability: Antibody: UniProt places it where antibodies can reach, with high confidence; its Gene Ontology location is reachable by antibodies, with medium confidence. PROTAC: ubiquitination databases record sites on it; its protein half-life has been measured.
Gene: Protein-coding gene on chromosome 17 (43,006,740 to 43,014,456, forward strand). Ensembl gene ENSG00000068079.
Subcellular location: Cytoplasm; Nucleus; Secreted
Subcellular location (Human Protein Atlas): Cytosol; Nucleoplasm; Nucleoli; Predicted to be secreted
Pathways (Reactome):
Immune System: Interferon alpha/beta signaling
Gene Ontology:
Molecular function: identical protein binding; protein binding
Biological process: macrophage activation involved in immune response; negative regulation of cell population proliferation; negative regulation of non-canonical NF-kappaB signal transduction; positive regulation of inflammatory response; positive regulation of innate immune response; positive regulation of toll-like receptor 4 signaling pathway; positive regulation of non-canonical NF-kappaB signal transduction; regulation of innate immune response
Cellular component: cytoplasm; cytosol; extracellular region; membrane; nucleolus; nucleoplasm; nucleus
Genetic constraint (gnomAD): Loss-of-function variants: 31 observed, 27.48 expected, observed/expected ratio (o/e) 1.13, 90% interval 0.85 to 1.52. The upper end of that interval is the gene's LOEUF score, 1.52, which puts it in group 6 of 6, group 1 being the genes least tolerant of losing a copy. Missense variants: 361 observed, 347.86 expected, observed/expected ratio (o/e) 1.04, 90% interval 0.95 to 1.13. Synonymous variants: 142 observed, 152.7 expected, observed/expected ratio (o/e) 0.93, 90% interval 0.81 to 1.07.
Homologues: Orthologues: chimpanzee IFI35 (99% identical), macaque IFI35 (76% identical), pig IFI35 (74% identical), dog IFI35 (74% identical), mouse Ifi35 (72% identical), rat Ifi35 (71% identical), guinea pig IFI35 (67% identical), tropical clawed frog ifi35 (35% identical), zebrafish ifi35 (34% identical). Paralogues in human: NMI (26% identical), RBM43 (14% identical).
Diseases named in the same sentence as IFI35 in open-access papers:
IFI35 is named in the same sentence as 45 diseases in open-access papers, as found by Europe PMC text mining. Sharing a sentence is not in itself a finding about the gene and the disease. The quoted sentences say what the papers report.
viral infections (18 papers, 2011 to 2023). "On the one hand, IFI35 can bind with Nmi or BTas after virus infection, thereby activating type I interferon antiviral response." (PMID 35844580, 2022). "To date, a series of studies demonstrated that IFI35 can bind to Nmi or BTas after viral infection, thereby activating type I interferon antiviral response." (PMID 35844580, 2022). "IFI35 is a leucine zipper protein and plays an important role in modulating virus infection, innate immune, and inflammatory responses by interacting with various host and viral proteins such as bovine Tas (BTas) regulatory protein of bovine foamy virus." (PMID 30809531, 2019). "Alternatively, the function of Ifi35 is different or more complex in an in vivo setting during viral infection." (PMID 29698474, 2018). "Our study is the first to provide a role for murine Ifi35 in modulating inflammatory response and IL-12p40/IL-12p80 production following virus infection in mice." (PMID 29698474, 2018). "Ifi35 has also been suggested to increase or decrease type I IFN in response to virus infection in in vitro culture settings." (PMID 29698474, 2018). "IFI35 is an IFN signaling regulator response to viral infections." (PMID 35625619, 2022). "It seems that fish IFI35 has different roles under different virus infections in different cells." (PMID 36557717, 2022). "Our study is the first to interrogate the function of Ifi35 during virus infection in vivo." (PMID 29698474, 2018). "IFI35 is involved in the antiviral functions of IFN against viral infections." (PMID 25844942, 2015). "Notably, IFI35 has dual roles in viral infections dependent on viral species." (PMID 37380972, 2023). "Human IFI35 was reported recently to negatively regulate the RIG-I antiviral signaling pathway and facilitate vesicular stomatitis virus replication, which is different to the majority of ISGs in antagonizing virus infections." (PMID 34335626, 2021). "In contrast to the classical role of ISGs in antagonizing virus infections, studies have also shown that IFI35 functions as a negative regulator of RIG-I-mediated antiviral signaling in vesicular stomatitis virus (VSV) infection." (PMID 30809531, 2019).
COVID-19 (9 papers, 2020 to 2025). A disease caused by infection with severe acute respiratory syndrome coronavirus 2. "Many studies have found that IFI35 plays an essential role in cytokine storms and severity in COVID-19 and influenza." (PMID 35625619, 2022). "Compared to healthy skin, COVID-19 explants exhibited significant expression of ISGs (IFI35, IRF7 and MX1), and this response was strongly reduced by H-151." (PMID 35045565, 2022). "Interferon-induced protein 35 (IFI35) is involved in the type I interferon signaling pathway and has been shown to be upregulated in patients with mild clinical COVID-19." (PMID 40877796, 2025). "IFI6, ISG15, IFI27, and IFI35 were increased in mild, and decreased or not changed in severe COVID-19, compared to healthy controls." (PMID 34108966, 2021).
colorectal cancer (7 papers, 2021 to 2025). A primary or metastatic malignant neoplasm that affects the colon or rectum. "We found that low expression of IFI35 in cancer tissue was associated with poor prognosis in patients with colorectal cancer." (PMID 37380972, 2023). "Evidence indicates that the expression of IFI35 in murine colorectal cancer cells is regulated by IFN-γ, with dependencies on STAT1 and IRF-7, thus establishing the IFN-γ/JAK/STAT1/IRF7/IFI35 pathway." (PMID 40909948, 2025). "Our proteomic data showed that the protein abundance of CD8 was positively correlated to that of IFI35 protein in samples from patients with colorectal cancer." (PMID 37380972, 2023). "A recent study demonstrated that the expression levels of IFI35 influence the radiosensitivity of colorectal cancer cells." (PMID 37380972, 2023). "In line with these, our study demonstrated that IFI35 plays a role in the immune environment of colorectal cancer." (PMID 37380972, 2023). "Together, our data demonstrated that higher IFI35 expression increased the number of CD8+ T in colorectal cancer." (PMID 37380972, 2023). "Next, we wish to exclude the possibility that IFI35 has a direct impact on the proliferation of colorectal cancer cells." (PMID 37380972, 2023). "First, we detected mRNA levels of IFI35 in normal tissues were significantly higher than the match colorectal cancer tissues." (PMID 37380972, 2023). "Consistently, IFI35 transcripts correlated with CD8+ T cells density with colorectal cancer samples in the TCGA-COAD dataset, as analyzed by the Timer website." (PMID 37380972, 2023). "To date, in the field of tumor biology, only a few studies revealed that IFI35 promoted the radiosensitivity of lung adenocarcinoma and colorectal cancer." (PMID 35844580, 2022). "However, it is imperative to note that the IFN-γ/JAK/STAT1/IRF-7/IFI35 pathway, as characterized in this study, has yet to be directly validated in vivo within a mouse model of colorectal cancer." (PMID 40909948, 2025). "Recent investigations have suggested that IFI35 may possess antitumor properties, and this idea is now confirmed in colorectal cancers." (PMID 40909948, 2025). "This analysis suggested that IFI35 protein may represent a promising novel target for improving immunotherapy sensitivity with colorectal cancer." (PMID 37380972, 2023). "This implies that IFI35 may play an essential role in regulating the colorectal cancer immune microenvironment in a CD8+ T cell dependent manner." (PMID 37380972, 2023). "However, there are still very few studies on IFI35 in tumor biology, among which mainly focused on enhanced radiosensitivity of lung adenocarcinoma and colorectal cancer." (PMID 35844580, 2022). "IFI35 could significantly inhibit the division of colorectal cancer cells, leading to a delay of cell entry into the G1 and S phases, thus leading to G2 phase arrest and shortening of the G1 and S phases." (PMID 34082779, 2021). "Furthermore, IFI35 protein enhanced the efficacy of CAR-T cells against colorectal cancer cells." (PMID 37380972, 2023). "In addition, IFI35 was reported to be involved in the regulation of radiosensitivity of colorectal cancer (CRC) cells, indicating that IFI35 might be a RT target for CRC." (PMID 34212001, 2021). "Therefore, the effect of IFN-γ-mediated IRF1 on the occurrence and development of colorectal cancer cells and radiosensitivity might be achieved by regulating IFI35." (PMID 34082779, 2021). "A research indicates that IFI35 promotes CD8+ T cell proliferation and cytotoxic activity through the PI3K/AKT/mTOR pathway in colorectal cancer, thus suppressing tumor growth." (PMID 40463715, 2025). "The transcriptional and proteomic analysis of the activation and cytotoxicity of CD8+ T cells in human cancer samples demonstrated that IFI35 expression is correlated with increased CD8+ T cell infiltration and predicted a better outcome in colorectal cancer." (PMID 37380972, 2023).
colorectal cancer (continued). "We found that IFI35 expression positively correlated with the activation of CD8+ T cells and with better overall survival in patients with colorectal cancer." (PMID 37380972, 2023). "Our findings identify IFI35 as a new biomarker that can enhance the proliferation and function of CD8+ T cells, as well as increase the efficacy of CAR-T cells against colorectal cancer cells." (PMID 37380972, 2023). "IFI35 inhibited the proliferation of colorectal cancer cell (CRC) after irradiation, suggesting the potential role of IFI35 in regulating the radiosensitivity of CRC cells." (PMID 34601503, 2021). "In conclusion, our study has revealed that IFI35 not only has the potential to serve as a novel biomarker that enhances the proliferation and function of CD8+ T cells, but also represents a promising therapeutic target for colorectal cancer." (PMID 37380972, 2023).
Sepsis (7 papers, 2017 to 2023). Sepsis is defined as life-threatening organ dysfunction caused by a dysregulated host response to infection. "IFI35, a secreted protein that acts as DAMPs to promote host inflammatory responses in sepsis, caught our attention as it has been identified as a mature functional protein and a potential therapeutic candidate for cancer treatment." (PMID 37380972, 2023). "One set of experiments confirmed that NMI and interferon-induced protein 35 knockout mice had reduced inflammation and mortality in a sepsis model." (PMID 36123652, 2022). "Moreover, IFI35 is a DAMP released by lipopolysaccharide (LPS)-activated macrophages to promote inflammatory responses in sepsis." (PMID 37380972, 2023). "Overall, through mouse study and online patient data analysis, five genes (CD247, DOCK2, IFI35, ITK, and LCK) were reported to positively correlate with sepsis prognosis whilst only the expression of MED25 displayed a negative correlation." (PMID 37456011, 2023). "CD247, DOCK2, IFI35, ITK, LCK, and MED25 might be important targets affecting the prognosis of sepsis." (PMID 33015708, 2020). "Sepsis development/progression in mice could be regulated by changing the LPS amount, as an example of using different doses of LPS to set survival and death groups in the discovery of six genes (CD247, DOCK2, IFI35, ITK, LCK and MED25)." (PMID 37456011, 2023).
lupus nephritis (3 papers, 2021 to 2022). Glomerulonephritis in the context of systemic lupus erythematosus. "have reported that IFI35 enhanced the proliferation of mesangial cells in patients with lupus nephritis." (PMID 35757684, 2022). "Additionally, IFI35 promotes the proliferation of mesangial cells, which is modulated by methyl CpG-binding domains in lupus nephritis." (PMID 35609018, 2022).
multiple sclerosis (3 papers, 2021 to 2025). A progressive autoimmune disorder affecting the central nervous system resulting in demyelination. "More recently, IFI35 has been proposed as a biomarker for neuroinflammation and for predicting long-term treatment response in multiple sclerosis patients." (PMID 40656995, 2025).
ZIKV infection (3 papers, 2019 to 2025). "Interferon-stimulated genes (ISG) such as MX2, IFIT1, IFIT3, IFITM1, IFI35, and RSAD2 (Viperin) were significantly upregulated after ZIKV infection." (PMID 30781519, 2019).
glioblastoma (2 papers, 2025). The most malignant astrocytic tumor (WHO grade IV). "Studies on glioblastoma multiforme (GBM) have also demonstrated the tumor-promoting role of IFI35, suggesting that inhibiting the expression of it could offer a promising strategy for enhancing GBM treatment." (PMID 40463715, 2025).
lung adenocarcinoma (2 papers, 2022 to 2023). A carcinoma that arises from the lung and is characterized by the presence of malignant glandular epithelial cells. "IFI35 is considered a radiotherapy‐associated gene and is associated with cellular immune responses, including in the proteasome accessory complex in lung adenocarcinoma." (PMID 36579897, 2023).
systemic lupus erythematosus (2 papers, 2011 to 2022). An autoimmune multi-organ disease typically associated with vasculopathy and autoantibody production. "The function of IFI35 also participates in the regulation of other inflammation-related diseases such as sepsis, liver injury, rheumatoid arthritis, and systemic lupus erythematosus (SLE)." (PMID 35740527, 2022).
Alzheimer disease (1 paper, 2021). A progressive, neurodegenerative disease characterized by loss of function and death of nerve cells in several areas of the brain leading to loss of cognitive function such as memory and language. "In summary, this study we have also identified important genes (NRG1, NEDD9, IRF5, IFI35, STAT1, STAT2, JAK2, IL3RA), and alterations in biological processes and pathways that may be associated with Alzheimer’s Disease." (PMID 34484988, 2021).
astrocytoma (1 paper, 2021). "IFI35 negatively regulates IFN-β phosphorylation of the STAT1-RIG-I-CXCL10/CCL5 axis in polyinosinic acid-polycytidylic acid-treated astrocytoma cells." (PMID 34082779, 2021). "IFI35 negatively regulates IFN-β phosphorylation in astrocytoma cells." (PMID 34082779, 2021).
atherosclerosis (1 paper, 2022). A disease characterized by the build-up of fatty material and calcium deposition in the arterial wall resulting in partial or complete occlusion of the arterial lumen. "Therefore, IFI35 may induce diverse diseases, including hyperplasia, atherosclerosis, and CVD after endothelial injury." (PMID 35955709, 2022).
breast carcinoma (1 paper, 2024). "Here we demonstrate that IFI35 is highly expressed in tumor tissues and can be induced by Interferon-γ in a time-dependent and concentration-dependent manner in breast cancer cells." (PMID 38216673, 2024). "From the TISCH scRNA-seq database, we found that IFI35 was widespread in various types of cells in breast cancer." (PMID 38216673, 2024).
cervical cancer (1 paper, 2024). A primary or metastatic malignant neoplasm involving the cervix. "Some studies have noted that IFN-γ can induce the expression of IFI35 in HeLa cervical cancer cells and THP-1 monocytes, as IFI35 is an IFN-inducible protein." (PMID 38216673, 2024).
colon adenocarcinoma (1 paper, 2023). "To determine the relevance of our findings in human Colon adenocarcinoma, we assessed IFNγ/STAT1/IRF7/IFI35/CD8 expression with Timer database." (PMID 37380972, 2023).